CDCP1 (CUB domain containing protein 1)
Diseases named in the same sentence as CDCP1 in open-access papers (continued):
Sharing a sentence is not in itself a finding about the gene and the disease.
autoimmune uveitis (2 papers, 2022). An autoimmune form of uveitis (disease). "Because the inflammatory cytokines IFN-γ, IL-17, and TNF-α have been implicated in the development of autoimmune uveitis in humans and in mice, we studied the effects of these cytokines on CDCP1 expression on aRPE-19 cells in vitro." (PMID 35951427, 2022). "CDCP1-KO mice developed attenuated retinal inflammation in a passive model of autoimmune uveitis, with disrupted tight junctions and infiltrating T cells detected in RPE flat mounts from WT but not CDCP1-KO mice during EAU development." (PMID 35951427, 2022). "Similar studies have been done to examine the role of CD6 and its ligand CD318/CDCP1 in autoimmune uveitis (EAU)." (PMID 36275816, 2022). "The observation of an identical distribution of CDCP1 protein expression in the human retina suggests that the mechanisms by which CDCP1 regulates EAU development in mice might also apply to humans with autoimmune uveitis." (PMID 35951427, 2022).
Cognitive impairment (2 papers, 2023 to 2024). Abnormal cognition is characterized by deficits in thinking, reasoning, or remembering. "Among the 52 inflammatory/immune proteins positively correlated with EDII score, six proteins (CXCL10, CCL3, HGF, OPG, CDCP1, NFATC3) were significantly associated with increased odds of incident cognitive impairment after adjusting for demographic characteristics and cardiovascular risk factors." (PMID 36737481, 2023). "Results provide insights into how inflammatory nutritional patterns are associated with an immune-related proteome and identify a group of proteins (CXCL10, CCL3, HGF, OPG, CDCP1, NFATC3, ITGA11) related to future cognitive impairment over a 14-year follow-up period." (PMID 36737481, 2023).
coronary artery disease (2 papers, 2025). "CDCP1 is also associated with higher incident ischemic heart disease risk (HR [95%CI] = 1.82 [1.17, 2.85])." (PMID 40684041, 2025). "Notably, a study of cardiovascular disease using Mendelian randomization revealed that CDCP1 is an important risk factor for coronary artery disease." (PMID 40599317, 2025).
cutaneous melanoma (2 papers, 2022 to 2025). A primary melanoma arising from atypical melanocytes in the skin. "Only adrenocortical carcinoma and cutaneous melanoma displayed mean transcript levels that were significantly lower in malignant versus normal tissues, while CDCP1 mRNA expression was not significantly modulated between normal and tumor in liver, prostate, rectum, thymus and uterus." (PMID 36276654, 2022).
endometrioid carcinoma (2 papers, 2019 to 2022). "Highest CDCP1 mRNA expression in tumor versus corresponding normal was seen in cholangiocarcinoma versus bile duct, endometrioid carcinoma versus endometrium, ovarian serous cystadenocarcinoma versus ovary, and PDAC versus pancreas." (PMID 36276654, 2022).
esophageal cancer (2 papers, 2015 to 2022). A primary or metastatic malignant neoplasm involving the esophagus. "For instance, increased CDCP1 expression correlated with poor prognosis in lung and colorectal but better outcomes in esophageal cancer." (PMID 26497208, 2015).
glioblastoma (2 papers, 2022). The most malignant astrocytic tumor (WHO grade IV). "There, genes with a higher expression in glioblastoma compared to astrocytoma were VEGFA, 4EBP1, CCL2, PLAU (uPA), CXCL8 (IL8), CXCL10 (IP10), CASP8, HGF, LIF, CD40, CDCp1, TNFRSF11B (OPG), CD274 (PD-L1), IL6, CXCL1, CCL20 (MIP3α), CCL8 (MCP2), CD244, MMP1, TNFRSF9, CXCL6, MMP10, FGF5)." (PMID 35301393, 2022).
hepatocellular carcinoma (2 papers, 2016). A malignant tumor that arises from hepatocytes. "Induction of CDCP1 by HIF-2α under hypoxic conditions has also been demonstrated in hepatocellular carcinoma where elevated CDCP1 expression also correlates with poor patient survival." (PMID 26973855, 2016).
hyperlipidemia (2 papers, 2011 to 2025). "Therefore, we will continue to use ApoE−/− mice to build a hyperlipidemia-induced arterial atherosclerosis model to verify the role of CDCP1 in lipid metabolism." (PMID 40256729, 2025). "We identified seven CNV regions that were associated significantly with hyperlipidemia and myocardial infarction in our patients through multistage analysis (P<0.001), at 1p21.3, 1q31.2 (CDC73), 1q42.2 (DISC1), 3p21.31 (CDCP1), 10q11.21 (RET) 12p12.3 (PIK3C2G) and 16q23.3 (CDH13), respectively." (PMID 22369086, 2011).
liver disease (2 papers, 2018 to 2023). "Disease annotations suggested three of the proteins are linked to different types of cancer (CDCP1, CCL3, ITGA11), whereas another two are related to liver diseases (CXCL10, HGF)." (PMID 36737481, 2023). "We identified a human hepatic stem/progenitor population in the CDCP1+CD90+CD66– subpopulation in human FLCs, indicating CDCP1 marker could potentially be utilized to identify and isolate HpSCs for further cytotherapy of liver disease." (PMID 29402311, 2018).
metastatic disease (2 papers, 2019 to 2020). "All data demonstrated that CDCP1 peptides were capable of triggering active immunity to inhibit 4T1 primary and metastatic tumor growth via activation of T lymphocytes." (PMID 32308755, 2020). "In addition, blocking of CDCP1 has been shown to be a potential mode for therapeutic intervention against metastatic disease." (PMID 31088477, 2019).
Obesity (2 papers, 2021 to 2025). Accumulation of substantial excess body fat. "The study reported associations between smoking, obesity, and altered expression of inflammatory markers such as IL-1α, CDCP1, TRAIL, and CD6." (PMID 40426647, 2025). "CDCP1, FGF23, HGF and IL-6 still had more prominent positive associations with %BF in overweight compared to normal weight subjects and the coefficients did not indicate that the associations were driven by obesity, whereas MCP-1 had a clear positive association with %BF only in the obese group." (PMID 34059769, 2021).
psoriasis (2 papers, 2022 to 2024). An autoimmune condition characterized by red, well-delineated plaques with silvery scales that are usually on the extensor surfaces and scalp. "Itolizumab, used for psoriasis, prevents CDCP1 from binding to CD6, leading to downregulation in T‐cell–mediated inflammation." (PMID 34338426, 2022).
uveitis (2 papers, 2022 to 2025). An inflammatory process affecting a part of or the entire uvea. "After uveitogenic T cells were adoptively transferred, CDCP1-KO mice developed significantly milder uveitis than WT mice, as indicated by markedly reduced clinical scores based on the indirect funduscopy results." (PMID 35951427, 2022). "We further investigated uveitis development in WT and CDCP1-KO mice on both C57BL/6 and DBA/1 backgrounds after the adoptive transfer of preactivated uveitogenic WT T cells using various ocular imaging techniques." (PMID 35951427, 2022). "Taken together, these data indicate strongly that CD6 on T cells might interact with its receptors, such as CDCP1, on the BRB to facilitate retinal infiltration and uveitis development." (PMID 35951427, 2022). "To rigorously confirm discovered role of CDCP1 in EAU, we also adoptively transferred the same numbers of uveitogenic T cells prepared from WT DBA/1 mice into WT and CDCP1-KO mice on the DBA/1 background and assessed the uveitis development using the same ocular imaging techniques." (PMID 35951427, 2022). "However, regarding its implication in induced uveitis in the mouse via the CUB domain-containing protein 1-CD6 axis, the presence and increased abundance of CUB domain-containing protein 1 in neutrophils is in alignment with the generally more activated equine neutrophils in ERU." (PMID 41154673, 2025).
allergic asthma (1 paper, 2023). A asthma with a basis in a pathological type I hypersensitivity reaction. "In our study, CDCP1 associated with both lean and overweight/obese asthma and with overweight/obese allergic and non‐allergic asthma, however not after adjusting for sex, BMI and body fat percentage." (PMID 36973952, 2023).
Ascites (1 paper, 2023). Accumulation of fluid in the peritoneal cavity (between the layers of the peritoneum that lines the abdomen). "The findings revealed that the expression of CDCP1 was elevated in the exosomes of OVCA patients with ascites [n = 9, p < 0.05, 95% confidence interval (CI) 65.74 to 385.1] while decreasing in their serum (n = 8, p < 0.0001, 95% CI -1675 to -829.0)." (PMID 37469398, 2023).
asthma (1 paper, 2023). "CUB domain‐containing protein 1 (CDCP1) has previously been suggested as a serum biomarker differentiating between poorly and well‐controlled asthma." (PMID 36973952, 2023).
atherosclerosis (1 paper, 2025). A disease characterized by the build-up of fatty material and calcium deposition in the arterial wall resulting in partial or complete occlusion of the arterial lumen. "Therefore, we need to continue to explore the mechanism of CDCP1’s influence on PDGFRβ endocytosis and intimal hyperplasia from multiple perspectives in order to provide a new treatment strategy for atherosclerosis in the future." (PMID 40256729, 2025). "However, based on RNA-seq analysis, we discovered CDCP1’s influence on abnormal lipid metabolism and atherosclerosis." (PMID 40256729, 2025).
Co-infection (1 paper, 2012). "Co-infection of inactive Src-KA and CDCP1 did not yield foci." (PMID 23300860, 2012).
colorectal tumors (1 paper, 2025). "CD318, also known as cub domain containing protein 1 (CDCP1), was overexpressed in many solid tumors and could be a promising target in treating colorectal tumors." (PMID 41228205, 2025).
esophageal adenocarcinoma (1 paper, 2018). A malignant tumor with glandular differentiation arising predominantly from Barrett mucosa in the lower third of the esophagus. "CDCP1 expression did not increase upon PDGF-BB treatment in the human large cell lung cancer cells NCI-H460 (ATCC® HTB-177TM), whereas it was slightly up-regulated in the human esophageal adenocarcinoma cells OE19 (Sigma-Aldrich)." (PMID 29792166, 2018).
hearing loss (1 paper, 2024). "This study investigated the causal relationships between various inflammatory proteins (including CCL19, CDCP1, and TSLP) and multiple types of hearing loss (SNHL, SIHL, and OHL)." (PMID 39677857, 2024).
heart failure (1 paper, 2026). Inability of the heart to pump blood at an adequate rate to meet tissue metabolic requirements. "Human genomic studies link reduced CUB domain-containing protein 1 (CDCP1) expression with myocardial recovery in heart failure." (PMID 42147194, 2026).
Hydrocephalus (1 paper, 2021). Hydrocephalus is an active distension of the ventricular system of the brain resulting from inadequate passage of CSF from its point of production within the cerebral ventricles to its point of absorption into the systemic circulation. "Although its physiological role in iNPH patients remains unclear, it can be speculated whether CDCP1 may serve as a diagnostic marker, potentially distinguishing iNPH from other types of hydrocephalus." (PMID 34863228, 2021).
hyperandrogenism (1 paper, 2024). Excessive secretion of androgens from the adrenal glands or gonads. "To be specific, we found that CDCP1 expression levels in PCOS had a significant positive correlation with neutrophils, suggesting that the neutrophil count increases accompanied by hyperandrogenism in PCOS, resulting in a chronic low-grade inflammation state." (PMID 39314522, 2024).
Hyperglycemia (1 paper, 2023). An increased concentration of glucose in the blood. "BMI correlated inversely with changes of PD-L1 and CD40 during hyperinsulinemia, Oncostatin-M, TNFSF14, FGF-21 and 4EBP-1 during hypoglycemia and CCL23, VEGF-A and CDCP1 during hyperglycemia (Rho ≤ -0.50)." (PMID 37400734, 2023).
hyperplasia (1 paper, 2025). An abnormal increase in the number of cells in an organ or a tissue with consequent enlargement. "In this work, we discovered CDCP1 expression was significantly higher in tissues affected by intimal hyperplasia and aimed to elucidate the mechanism of CDCP1 in intimal hyperplasia." (PMID 40256729, 2025).
idiopathic pulmonary fibrosis (1 paper, 2022). Idiopathic pulmonary fibrosis (IPF) is a nonneoplastic pulmonary disease that is characterized by the formation of scar tissue within the lungs in the absence of any known cause. "CDCP1 is present on interstitial fibroblasts, but not myofibroblasts, in normal lungs and those with idiopathic pulmonary fibrosis." (PMID 35172279, 2022).
intracranial aneurysm (1 paper, 2024). "For genetically predicted CDCP1, it was only possible to assess the association with risk for intracranial aneurysm using a single IV; this identified a significant association (OR = 1.32 [95% CI: 1.08 to 1.61], p = 6.93 × 10−3)." (PMID 38762535, 2024). "For CDCP1, the sensitivity analyses identified a consistent, although non-significant, effect estimate for the association with risk for intracranial aneurysm." (PMID 38762535, 2024). "A one standard deviation higher level of genetically predicted plasma CDCP1 was associated with an increased risk of intracranial aneurysm (OR = 1.22 [95% CI: 1.02 to 1.47], p = 0.0280)." (PMID 38762535, 2024). "Mendelian randomisation analyses suggested higher CA14 levels might cause larger hippocampal volume and increased stroke risk, whilst higher CDCP1 levels might increase intracranial aneurysm risk." (PMID 38762535, 2024).
liver cancer (1 paper, 2024). An epithelial or non-epithelial malignant neoplasm that arises from the liver. "Combining with previous studies, we infer that CDCP1 may promote the transformation of ALD into alcohol-related liver cancer." (PMID 39497803, 2024).
lung disease (1 paper, 2022). "In conclusion, although the long-term impact of high serum levels of CDCP1 is still unknown, we should be alert to the potential implications for lung disease." (PMID 35172279, 2022).
mastocytosis (1 paper, 2023). A clonal myeloproliferative neoplasm characterized by the proliferation and accumulation of neoplastic mast cells in one or multiple organs or organ systems. "According to a recent study in adults, E-selectin, adrenomedullin, T-cell immunoglobulin, mucin domain 1, and CUB domain-containing protein 1 (CDCP1)/CD138 were other proteins elevated in mastocytosis." (PMID 36766791, 2023).
metastatic cancer (1 paper, 2012). A carcinoma which has spread from the original site of growth to another anatomic site. "Generally, CDCP1 is highly phosphorylated and functionally activated in metastatic cancer; dysregulated expression of CDCP1 is associated with tumor malignancy." (PMID 22390300, 2012).
metastatic prostate carcinoma (1 paper, 2015). A carcinoma that arises from the prostate gland and has spread to other anatomic sites. "We recently described a targeted approach for cell surface glycoprotein analysis and observed that CUB-domain-containing protein 1 (CDCP1) was over-expressed in metastatic prostate cancer." (PMID 26497208, 2015).
migraine (1 paper, 2024). "However, further research is needed to fully elucidate the mechanistic link between cigarette smoke, IL-1α and CDCP1 elevation, and migraine pathogenesis." (PMID 39170074, 2024).
oral cancer (1 paper, 2024). "The median IRS of CDCP1 and t-PA were also found to be positively, albeit moderately, correlated with the distinct degrees of OSCC differentiation, suggesting that CDCP1 and t-PA may be associated with aggressiveness of oral cancer as well." (PMID 39441449, 2024).
osteonecrosis (1 paper, 2025). A none disease characterized by death of bone tissue due to a lack of blood supply. "Osteonecrosis and the CDCP1 cytokine showed a positive correlation, suggesting a causal relationship between CDCP1 and an elevated risk of osteonecrosis (IVW OR = 1.23, 95% CI = 1.01–1.50, P = .037)." (PMID 40760551, 2025). "A link between CDCP1 and a higher risk of osteonecrosis has been revealed by genetic data (IVW OR = 1.23, 95% CI = 1.01–1.50, P = .037)." (PMID 40760551, 2025).
rectal cancer (1 paper, 2025). A primary or metastatic malignant neoplasm that affects the rectum. "Interrogation of TCGA/GTEx cohorts demonstrated that CDCP1 expression was significantly higher in colon (n = 455) and rectal cancers (n = 165) compared with normal colorectal tissues (n = 830)." (PMID 41301830, 2025).
skin cancer (1 paper, 2015). "Since the initial description of this protein in 2001, high levels of CDCP1 have been shown to be associated with a higher frequency of solid tumors in various models, including colon, prostate, pancreas, lung, renal and skin cancers." (PMID 25876044, 2015).
squamous cell carcinoma (1 paper, 2022). A carcinoma arising from squamous epithelial cells. "JAG1 and CDCP1 were highly expressed in patients with squamous cell carcinoma, whereas FAP-α was highly expressed in patients with adenocarcinoma in our analysis." (PMID 35054034, 2022). "JAG1 and CDCP1 were mainly highly expressed in the squamous cell carcinoma group, while FAP-α was highly expressed in the adenocarcinoma group." (PMID 35054034, 2022).
steatosis (1 paper, 2022). Increased lipid within the cytoplasm of cells. "Besides, CDCP1 also acts as a profibrotic mediator which may play a central role in subjects with severe steatosis and fibrosis." (PMID 35128832, 2022). "Except the plasma level of CDCP1 which is significantly lower in mild steatosis and significantly higher in severe steatosis versus no steatosis, majority of the proteins followed the same directional changes in all steatosis groups." (PMID 35128832, 2022). "It has been reported that CDCP1 knockout mice have increased lipid accumulation in the liver which may explain the downregulation of CDCP1 in mild steatosis compared with no steatosis in our study." (PMID 35128832, 2022).